TNF (tumor necrosis factor)
Diseases named in the same sentence as TNF in open-access papers (continued):
Sharing a sentence is not in itself a finding about the gene and the disease.
diabetes (continued). "In early stages of diabetes the frequency and hence number of TNFα producing CD68+F4/80− macrophages are higher compared to healthy control mice." (PMID 24594974, 2014). "Female, diabetes, hypertension, history of CKD, hyperuricemia, high level of cholesterol, and high sensitivity C-reactive protein (hsCRP) (≥1.03 mg/L) and TNF-α levels (≥1.12 ng/L) were independently associated with an increased risk of albuminuria." (PMID 23951003, 2013). "TNF-α levels are elevated in diabetes in part through increased oxidative stress that promotes inflammation." (PMID 23484152, 2013). "This work confirms previous studies demonstrating diabetes-induced reductions in peripheral nerve tissue of cytokines such as IL-6, TNFα and CNTF." (PMID 24152426, 2013). "Age above the median (42 years) was associated with lower odds of elevated IL-10, self-reported high cholesterol and diabetes with higher odds of elevated TNF-α, and current ART use with lower odds of elevated TNF-α." (PMID 23987993, 2013). "Experimental diabetes significantly increases the TNF-α level (from 3.8 ± 0.5 pg/mg to 9.7 ± 1.0 pg/mg; P < 0.001)." (PMID 23762874, 2013). "The current study showed that quercetin attenuates the increase in the serum level of TNF-α in both models of diabetes." (PMID 23717483, 2013). "In contrast, the proinflammatory background of diabetes, which includes increased placental levels of TNFα, IFNγ, and IL-1β, promotes enhanced CX3CL1 gene expression." (PMID 23956503, 2013). "Since elevated IL-1β, IL-6, and TNF-α were referred to as independent predictors of diabetes, decreased concentrations reveal the antidiabetic properties of functional food." (PMID 23690866, 2013). "The present in vivo study supports the concept that diabetes is associated with increased AGE accumulation and up-regulation of the inflammatory cytokine TNFα." (PMID 23691192, 2013). "It is known that diabetes induces the expression of various cytokines, such as TNF-α and IL-6, by immune cells." (PMID 24000330, 2013). "A high level of urinary TNF-α is correlated with renal injury and a disruption of the glomerular permeability barrier in patients with diabetes." (PMID 24250725, 2013). "In our current study, IMD administration decreased diabetes-induced myocardial NF-κB activation, cytochrome C oxidase expression, and serum/myocardial TNF-α, IL-1, and IL-6 expression." (PMID 23777472, 2013). "Activated MC/MPs express inflammatory cytokines such as CCL2, TNFα, and IL-1β in experimental diabetes." (PMID 24278148, 2013). "Thus, we hypothesize that the diabetes-induced, systemic loss of β2-adrenergic receptor input to retinal cells, causes further damage to the retina by triggering production of TNFα, which in turn disables the anti-apoptotic actions of insulin receptor pathways." (PMID 23894672, 2013). "The renal expression of inflammatory cytokines such as TNF-α, IL-6 and IL-1β were demonstrated to increase in diabetes, contributing to the development of DN." (PMID 24499158, 2013). "In vivo, FOXO1 DNA activity is increased twofold in diabetic wounds, and the increase is driven by diabetes-enhanced TNF levels." (PMID 23484152, 2013). "Kolaviron prevented diabetes induced increase in the hepatic levels of proinflammatory cytokines; interleukin (IL)-1beta, IL-6, tumour necrosis factor (TNF-α) and monocyte chemotactic protein (MCP-1)." (PMID 24359406, 2013). "Meanwhile, development of active TB depends largely on endogenous factors including HIV/AIDS, radiographic evidence of old healed TB, diabetes mellitus, chronic renal failure, immunosuppressive treatment such as TNF-α inhibitors and use of steroids." (PMID 23914947, 2013). "Post-prandial inflammation is characterized by an increase in IL-6 and TNF-α in both normal individuals and those with diabetes." (PMID 23844276, 2013). "TNF inhibition attenuates the impact of diabetes-enhanced TNF-α, which offers potentially new therapeutic avenue for treatment of abnormally diabetic wounds healing." (PMID 23484152, 2013).
diabetes (continued). "Elevation of TNF-alpha and IL-6 was detected in diabetes, which was related to the progression of diabetic complications." (PMID 23853776, 2013). "Increased levels of pro-inflammatory cytokines MCP-1, IL-1β, IL-6, IL-18 and TNF-α have been reported in diabetes." (PMID 24359406, 2013). "Thiazolidinediones (TZDs), the insulin-sensitizing drugs, antagonize TNFα-induced lipolysis in adipocytes, thereby increasing insulin sensitivity in diabetes patients." (PMID 23951179, 2013). "The renal expression of inflammatory cytokines such as TNF-α and IL-1β was demonstrated to increase in diabetes, contributing to the development of DN." (PMID 24027593, 2013). "TNF-α increased in the lycopene and lycopene-diabetes group with regard to the control group, but this increase was not statistically significant." (PMID 23780417, 2013). "Western blotting revealed that both diabetes and Zn deficiency significantly up-regulated the expression of PAI-1, TNF-α, and ICAM-1." (PMID 23251339, 2012). "Paradoxically, long-term treatment with tumor necrosis factor alpha (TNF-α) as well as short-term treatment with anti-TNF-α prevent the later development of diabetes in NOD mice." (PMID 22606220, 2012). "Based on the literature on other cell types, with the onset of diabetes, TNFα preferentially phosphorylates Ser307 on IRS-1." (PMID 22328823, 2012). "Although the possible relevance of cytokines such as Il-6 and TNF-α to ADT-related diabetes has been suggested, its mechanism is poorly understood." (PMID 22792092, 2012). "In other two reports, the increase in TNF-α was found in rats with durations of diabetes similar to those of our studies." (PMID 22615852, 2012). "Exclusion of individuals with diabetes resulted in attenuated effect estimates for IL-6, VEGF, and TNF-α, suggesting that some of the effects were attributable to individuals with diabetes." (PMID 22336131, 2012). "So far, the only reported cases of hypoglycemia have occurred in individuals who were treated with TNF-α inhibitors and who had a known history of diabetes." (PMID 22234148, 2012). "The potential role of TNF-α in the pathogenesis of diabetes is interesting and somewhat controversial." (PMID 22606220, 2012). "Circulating oxidized LDL-containing immune complexes (oxLDL-IC) are increased in diabetes stimulate synthesis of IgGs in addition to other proinflammatory cytokines such as IL-1β, IL-6, IL-18, and TNF-α in Mono Mac 6 cells and primary human macrophages." (PMID 23267348, 2012). "Type 2 diabetes mellitus and insulin resistance (IR) are characterized by the release of pro-inflammatory cytokines, such as TNFα and IL-6, resulting in an inflammatory state." (PMID 23166628, 2012). "For the serum biomarkers, subjects with incident diabetes had lower levels of adiponectin (P = 0.001), but higher levels of hsCRP (P<0.001), IL-6 (P = 0.014), TNF-α R2 (P<0.001) and A-FABP (P<0.001)." (PMID 22615828, 2012). "As noted herein tumor necrosis factor alpha (TNF-α) immerged as a potential therapeutic target for new onset diabetes." (PMID 22606220, 2012). "If rodents that possess PPARG with Pro12 consume a high-fat diet, the small-sized adipocytes accumulate more fat to change to hypertrophic adipocytes, which secrete factors that promote diabetes mellitus, such as TNFα, resistin and free fatty acids." (PMID 22937051, 2012). "A biomarker risk score, derived from the number of biomarkers predictive of diabetes (low adiponectin, high TNF-α R2), had similar performance when added to the CDP model (AUC = 0.829 [95% CI: 0.808–0.849])." (PMID 22615828, 2012). "The literature describes episodes of hypoglycemia occurring in those with pre-existing diabetes and concurrent use of TNF-α inhibitors." (PMID 22234148, 2012). "It is possible that TNF inhibitors magnify the clinical effects of hypoglycemia in patients with already-treated diabetes." (PMID 22234148, 2012).
diabetes (continued). "Diabetes resulted in a noticeable increase in IL-6 (26.5 ± 6.3 vs 17.1 ± 4.7 pg/mg protein, P < 0.05) and TNF-α (89.7 ± 10.2 vs 55.9 ± 9.5 pg/mg protein, P < 0.05) compared with the control group." (PMID 21232147, 2011). "it was demonstrated that diabetes increased proinflammatory cytokines including TNF-α, IL-1β and IL-6 in the circulating, renal production, and urinary excretion." (PMID 21699681, 2011). "Vitamin E supplementation in patients with diabetes decreases the levels of proinflammatory cytokines, such as IL-1, TNF-α, IL-6, and reactive C protein, in serum and stimulated monocytes." (PMID 21352586, 2011). "TSN decreased the levels of IL-6 (20.3 ± 5.5 vs 26.5 ± 6.3 pg/mg protein, P < 0.05) and TNF-α (69.0 ± 12.4 vs 89.7 ± 10.2 pg/mg protein, P < 0.05) compared with the diabetes group." (PMID 21232147, 2011). "The cytokine levels of TNF-α, IL-1β, and IL-6 were increased in the patients with diabetes and diabetic rats." (PMID 21716679, 2011). "RMD also inhibited diabetes-induced elevation in the levels of interleukin (IL)-1β, IL-6, interferon-γ and tumor necrosis factor-α." (PMID 21716679, 2011). "In the retinas of diabetic wt mice, we also found significantly increased levels of TNFα, IL-6 and IL-1β mRNA expression and a tendency to increased IFNγ and caspase-1 mRNA, indicating some degree of local inflammation after 8 weeks of diabetes." (PMID 20856927, 2010). "The increased TNF-α expression induces the production of ROS, leading to endothelial dysfunction in diabetes." (PMID 21234421, 2010). "Individuals with type 2 diabetes mellitus overexpress TNF-α in adipose tissue; this TNF-α spills into the circulation, inhibiting the action of insulin in metabolically active tissue such as skeletal muscle." (PMID 21253481, 2010). "A very recent study with T1DM and T2DM rats shows that TNFα plays an important role in microvascular apoptosis in diabetes." (PMID 20634940, 2010). "mRNA as well as protein levels for tumor necrosis factor α (TNF-α), a robust marker of inflammation, were increased in the retina early in the course of diabetes." (PMID 21042558, 2010). "The third aim of the present study was to evaluate the influence of TNFα on endothelial VCAM-1 expression in diabetes and/or dyslipidemia, using TNFα knockout mice." (PMID 20856927, 2010). "TNFα has been proposed as a link between metabolic dysregulation and inflammation and/or vascular dysfunction in diabetes, and it is well established as a key molecule in diabetic retinopathy." (PMID 20856927, 2010). "Several well-known markers of inflammation secreted by the adipose tissue, including IL-6 (which stimulated the hepatic synthesis of CRP), IL-1β and TNF-α, have been referred as independent predictors of diabetes." (PMID 20652060, 2010). "In wt mice, diabetes resulted in a clear increase in TNFα, IL-6 and IL-1β mRNA expression levels (p<0.01, p<0.01 and p<0.05, respectively) and in a tendency to higher IFNγ and caspase-1 mRNA levels (n.s.)." (PMID 20856927, 2010). "Diabetes increased chondrocyte apoptosis through a mechanism that involved enhanced production of TNF-α, which stimulates chondrocyte apoptosis and upregulates mRNA levels of apoptotic genes through FOXO1 activation." (PMID 20200974, 2010). "The in vitro and in vivo bioassay data in this study demonstrated the ability of genistein to counteract retinal inflammation during diabetes by dampening of microglia activation and TNF-α-release." (PMID 21042558, 2010). "As with most if not all of the other diseases we review here, studies of pro-inflammatory markers (such as TNF-α, IL-1 and C-reactive protein) during the development of diabetes show its aetiology to be inflammatory in nature." (PMID 19133145, 2009). "We now show that the soluble TNF-α inhibitor etanercept significantly reduces retinal cell apoptosis, caspase activation and long-term complications during the course of diabetes in the eye." (PMID 19641635, 2009).
diabetes (continued). "We investigated the involvement of tumor necrosis factor α (TNF-α) in diabetes-related histopathological changes in two relevant rodent models." (PMID 19641635, 2009). "In conclusion, our data indicate that the proinflammatory cytokine TNF-α plays a major role in endothelial and retinal cell injury and apoptosis during diabetes." (PMID 19641635, 2009). "Diabetes is an inflammatory condition in which up-regulation of inflammatory markers such as tumor necrosis factor (TNF)-α leads to impaired insulin signaling." (PMID 19825152, 2009). "The direct implication of TNF-α levels in diabetes points to the key role inflammation plays in pathogenesis." (PMID 19558671, 2009). "The significant inhibition of the diabetes-induced activation of caspase 8 and 3 in our model leads to the conclusion that TNF-α induces retinal cell death in diabetes through these two caspases." (PMID 19641635, 2009). "Late expression of TNFα in the RIP-GP-TNFα mouse model reduced the incidence of diabetes to ~35% and, additionally, reversion from clinically overt diabetes to normoglycemia occurred in up to 50% of the mice." (PMID 23675028, 2007). "NOD mice are known to express an allelic variant of one of the receptors for TNF, TNFR2, that is distinct from that expressed by the diabetes resistant C57BL6 strain." (PMID 17254331, 2007). "As expected, the exact time of TNFα expression was very important for the influence of TNFα on diabetes pathogenesis in LCMV-infected RIP-GP-TNFα mice and revealed a dual role of TNFα." (PMID 23675028, 2007). "Nanoflowers demonstrate rapid wound healing due to reduced inflammation, tissue regeneration, and angiogenesis in the diabetes-induced wound model by modulating tumor necrosis factor-α, CD-44, Ki-67, collagen deposition, ROS, interleukin-1β (IL-1β), IL-8, and IL-6 expression." (PMID 41737838, 2026). "Recently, a study focusing on sensory ganglia SGCs showed that activated SGCs release more IL-6 and TNF-α after a tissue injury to escalate neuronal hypersensitivity and chronic pain, which reflects that diabetes (i.e., hyperglycemia) triggers cytokine-induced sympathetic inflammation." (PMID 41596372, 2026). "Hyperglycemia and dyslipidemia result in the elevated circulating levels of proinflammatory cytokines, such as tumor necrosis factor alpha (TNF-α), interleukin-6 (IL-6), interleukin-1β (IL-1β), and C-reactive protein (CRP) which, in turn, increase the risk of diabetes and vascular complications." (PMID 40004134, 2025). "By analyzing the correlation between TNF-α and glycolipid metabolism indicators, this study aims to provide a scientific basis for clinical treatment and further clarify the interaction between diabetes and periodontitis." (PMID 41244040, 2025). "Pro-inflammatory cytokines, including IL-6 and TNF-α, and ROS production are increased in both type 1 and type 2 diabetes mellitus, although the degree may be higher in type 1 diabetes mellitus." (PMID 40862723, 2025). "The abnormal elevation of pro-inflammatory cytokines (such as TNF-α, IL-1βand IL-6) may exacerbate islet dysfunction in individuals with diabetes." (PMID 41300029, 2025). "Diabetes is often accompanied by activation of the inflammatory system, which a.o. includes pancreatic tissue infiltration of monocytes and macrophages that locally secrete inflammatory cytokines like TNF-α." (PMID 40308759, 2025). "Similarly, systemic inflammatory molecules such as TNF-α and IFN-γ have also been associated with a poor prognosis in these comorbid conditions of diabetes and cardiovascular diseases." (PMID 40137715, 2025). "The presence of TNF-α, IL-6, and IL-12 mRNA could suggest early chronic inflammation in the vascular systems of individuals with diabetes, indicating the potential development of further diabetic complications." (PMID 40298831, 2025). "Among these, the TNF pathway is significant in connecting BC and diabetes." (PMID 40547917, 2025).
diabetes (continued). "Likewise, KEGG analysis revealed that DE-NMRGs were enriched in the AGE-RAGE signaling pathway, the IL-17 signaling pathway, the TNF signaling pathway, etc., in patients with diabetes-related complications." (PMID 40282274, 2025). "Even if diabetes does not develop, long-term hyperglycemia is known to increase plasma values of cytokines such as TNF-α, IL-6, and VEGF, causing retinopathy-like changes." (PMID 41578817, 2025). "Additionally, it has been reported that Myrt administration reduces elevated levels of NF‐κB, TNF‐α, and IL‐1β in liver and pancreatic tissues in a rat model of Type 2 Diabetes Mellitus." (PMID 40025781, 2025). "Additionally, when looking at circulating levels of TNF‐α in patients with diabetes, patients with DFUs had higher levels of TNF‐α, high‐sensitivity C‐reactive protein (hsCRP) and IL‐6 compared to those without a DFU." (PMID 40888511, 2025). "Elevated TNF‐α levels in diabetes also activate FOXO1, which regulates apoptosis." (PMID 40888511, 2025). "In addition, PCs also play a key role in the prevention and control of diabetes and its complications by regulating cytokines such as IL-1β, TNF-α, and IL-12 to reduce the inflammatory response." (PMID 40864768, 2025). "Univariate analysis showed that diabetes, preoperative serum CK levels, serum IL-6, and TNF-α levels at postoperative day 3 were associated with early LFCN injury, while diabetes, BMI, and postoperative inflammation were significantly associated with persistent LFCN injury." (PMID 40236989, 2025). "Combining TNF inhibitors with treatments specific to metabolic or cancer conditions may offer synergistic benefits, particularly for patients with both diabetes and BC." (PMID 40547917, 2025). "Metabolic regulation: Insulin signaling pathway showed nodal connections with both glucagon signaling and inflammatory pathways (IL-17 signaling, TNF signaling), proposing a unique therapeutic strategy for diabetes complications via metabolic-inflammatory crosstalk regulation." (PMID 41295287, 2025). "This modulation may influence the expression of key inflammatory mediators such as tumor necrosis factor-α (TNF-α), thereby improving the wound microenvironment in diabetes." (PMID 41356003, 2025). "TNF-α, IL-1β, IL-6, NF-κB and IL-17A are multifunctional cytokines, that are mainly related to immune regulation, and play a crucial role in the occurrence and progression of diabetes." (PMID 40046742, 2025). "The blood-brain barrier might be harmed in a diabetes-induced inflammatory environment under the influence of elevated interleukin (IL)-1β, IL-6, tumor necrosis factor (TNF)-α levels, and advanced glycation end products (AGEs) accumulation." (PMID 40771927, 2025). "Additionally, positive associations were noted between: EDT and age and diabetes duration (r = 0.416, p < 0.001 and r = 0.290, p = 0.008, respectively), IVRT and HbA1c (r = 0.237, p = 0.036), E/e’ and TNF-alpha (r = 0.260, p = 0.02)." (PMID 40869598, 2025). "Rhein reduced the expressions of inflammatory markers (TNF-α and IL-6), hexosamine, and mitogen-activated protein kinase p38 pathways, and could potentially prevent oxidative complications induced by diabetes." (PMID 39942768, 2025). "Higher serum C-reactive protein levels (6.6 ± 12.3 mg/dL, p = 0.04) along with higher levels of pro-inflammatory cytokines IL-6 (1.59 ± 1.19, pg/mL, p = 0.01) and TNF-α (1.49 ± 0.55 pg/mL, p = 0.01) indicated greater systemic inflammation in participants with diabetes." (PMID 40533477, 2025). "Regarding inflammatory biomarkers, elevated proinflammatory cytokines in plasma such as TNF-α could influence the development of diabetes." (PMID 41283421, 2025). "In people with diabetes, there is often a persistent state of low-grade inflammation, marked by increased levels of pro-inflammatory substances like tumor necrosis factor-alpha (TNF-α) and interleukin-6 (IL-6)." (PMID 41268323, 2025). "In fact, TNF-α has been shown to be related to the ESRD in diabetes." (PMID 39941397, 2025).